SNORD114-20 (small nucleolar RNA, C/D box 114-20)
Synonyms: 14q(II-20)
Gene: Small nucleolar RNA gene on chromosome 14 (100,981,004 to 100,981,075, forward strand). Ensembl gene ENSG00000202048.
Gene Ontology:
Biological process: RNA processing
Cellular component: nucleolus
Homologues: Orthologues: chimpanzee SNORD114-20 (100% identical), macaque SNORD114-20 (92% identical), rat Snord114-9 (65% identical). Paralogues in human: SNORD114-23 (92% identical), SNORD114-29 (92% identical), SNORD114-25 (89% identical), SNORD114-28 (88% identical), SNORD114-15 (86% identical), SNORD114-22 (86% identical), SNORD114-26 (86% identical), SNORD114-5 (86% identical), SNORD114-9 (86% identical), SNORD114-21 (85% identical), SNORD114-24 (82% identical), SNORD114-3 (82% identical), and 26 more.